BRCA1 (BRCA1 DNA repair associated)
Diseases named in the same sentence as BRCA1 in open-access papers (continued):
Sharing a sentence is not in itself a finding about the gene and the disease.
breast cancer (continued). "The data collected refers to patients diagnosed with breast cancer diagnosed before 2007; BRCA1/2 gene mutation carriers were not included in the analysis, which may be due to diagnostic limitations at that time." (PMID 35887761, 2022). "Because the number of BRCA1/2 genetic testing performed in our department so small before the approval of BRACAnalysis® for HBOC in primary breast cancers, we did not have enough data to discuss the association between the presence of BRCA1/2 mutation carrier and their prognosis." (PMID 35191009, 2022). "However, the existing literature does not suggest an increase in breast cancer risk in the specific cohort of BRCA1/2 healthy carriers undergoing HRT, even before breast surgery." (PMID 35884518, 2022). "In line with this, the burden of TAI and LOH could successfully predict (AUC = 0.74) the response of breast cancer patients to cisplatin in two phase 2 clinical trials (NCT00148694 and NCT00580333), an association that remained significant when only wild-type BRCA1/2 cases were included." (PMID 36077694, 2022). "Interestingly, arginine methylation of BRCA1 was significantly higher in breast cancer cells than in normal breast cells, suggesting it may affect the tumor suppressor function of BRCA1." (PMID 36077176, 2022). "In addition, the last V5 version of BOADICEA incorporates the effects of pathogenic variants (PVs), not only in BRCA1 and BRCA2 genes, but also in PALB2, CHEK2, ATM and BARD1 for the breast cancer model and RAD51D, RAD51C and BRIP1 for the ovarian cancer model." (PMID 35886069, 2022). "Similarly, germline breast cancer susceptibility gene variants, such as BRCA1 and BRCA2, are not considered to contribute towards the traditional definition of a cancerized field." (PMID 35362092, 2022). "Therefore, lower levels of HspBP1 in the nucleus may be a characteristic biological marker for breast cancers that express wild-type BRCA1." (PMID 35387978, 2022). "The presented data indicate that pregnancy after completion of oncological treatment for breast cancer does not affect the prognosis of patients, regardless of BRCA1/2 gene mutation status and hormone receptor expression and does not affect the well-being of the children born." (PMID 35887761, 2022). "Thus, we used the ER-negative SNP set due to its strong connection to BRCA1 breast cancer." (PMID 35118379, 2022). "An example of this is PARP inhibitors, which have been approved for breast cancers in both the metastatic and the early-stage setting for patients with germline pathogenic BRCA1 or BRCA2 mutations, and for ovarian, pancreatic, and prostate cancers with BRCA1 or BRCA2 mutations." (PMID 35703177, 2022). "Consequently, systemic delivery of a STING agonist combined with PARPi elicits robust anti-tumor immunity and demonstrates significant therapeutic efficacy in Brca1-deficient mouse models of breast cancer regardless of tumor cell-intrinsic STING expression." (PMID 35641483, 2022). "To investigate whether the levels of HspBP1 expression affect tumorigenesis in breast cancer, we stably depleted HspBP1 in BRCA1-proficient (MCF-7 and MDA-MB-231) and BRCA1-deficient (MDA-MB-436) breast cancer cells using HspBP1-specific shRNAs and stably overexpressed GFP-HspBP1 in each cell line." (PMID 35387978, 2022). "Additionally, oncoprint analysis showed that BRCA1 and BRCA2 mutations, whether germline or somatic, were mutually exclusive in ovarian cancer and breast cancer." (PMID 34979999, 2022). "Pathogenic variants in BRCA1 and BRCA2 genes account for approximately 50% of all hereditary BC, with 60-80% of patients characterized by Triple Negative Breast Cancer (TNBC) at an early stage phenotype." (PMID 36741700, 2022).
breast cancer (continued). "Here we report the identification of DDB1 and CUL4-associated factor 8-like protein 1(DCAF8L1), a novel DCAF protein which is encoded by an X-linked gene, plays crucial role in targeting BRCA1/BARD1 for proteasomal degradation, and might be involved in the development of breast cancer." (PMID 35280675, 2022). "Interestingly, the classic breast cancer marker genes, BRCA1 and CD44 were overexpressed in the PABC PPI network, suggesting that PABC may be characterized by higher activity of proteins that contribute to NPABC." (PMID 36035177, 2022). "Therefore, the crosstalk of AR, EGFR, and BRCA1 may affect the significance of AR in breast cancers, especially in TNBC." (PMID 35053220, 2022). "Moreover, 914 breast cancer patients (8.3%) carried a CHEK2 mutation (659 missense mutations and 255 protein-truncating mutations (47 1100delC; 91 IVS2 + 1G/A and 117 del5395 mutations) and 502 breast cancer patients (4.6%) carried a BRCA1 mutation." (PMID 35205705, 2022). "However, a growing body of evidence indicates that BRCA1 and BRCA2 TN as well as luminal cancers are more chemosensitive and achieve higher pathologic complete response (pCR) rates compared with breast cancer without the BRCA1 or BRCA2 pathogenic variant." (PMID 36580360, 2022). "Furthermore, the reversion mutations were not only detected in BRCA1/2, but also in other HRR pathway genes including RAD51C, RAD51D, and PALB2 in ovarian, prostate, and breast carcinomas as a mechanism of acquired resistance to platinum-based chemotherapies and PARPIs." (PMID 35785170, 2022). "The genes BRCA1 (OMIM accession number: 113705) and BRCA2 (OMIM accession number: 600185) were discovered in the mid‐1990s and are considered “high penetrance” because mutations confer, by some estimates, a greater than 80% lifetime risk for female breast cancer." (PMID 36054727, 2022). "Interestingly, it was shown that BRCA1 may be required for DNA repair so important in breast cancer development." (PMID 34326920, 2021). "Thirteen, 12, 10, 18, 9, and 12 studies reported data regarding the association between BRCA1 gene methylation status and breast cancer histology, disease stage, tumor grading, patients’ lymph nodal status, disease molecular classification, and patients’ menopausal status, respectively." (PMID 33808555, 2021). "Interestingly, human BRCA1-associated breast cancers have been shown to have lower levels of SIRT1 than their normal controls, an effect likely caused via the transcriptional effects of BRCA1 on SIRT1 expression." (PMID 34750509, 2021). "Clinicians may discuss this issue with BRCA1/2 variant carriers who may face a high risk of contralateral breast cancer regardless of BCT or mastectomy." (PMID 33890992, 2021). "Overexpression of protein CDC42 in breast cancer could induce the signaling to TF BRCA1." (PMID 33802957, 2021). "It has been reported that depletion of the HR proteins such as BRCA1/2 in breast cancer cells could stimulate synthetic lethality in PARG‐inhibited cells, and that COH34, a PARG inhibitor, is able to induce cell death of ovarian and breast cancers with BRCA mutations or resistance to olaparib." (PMID 34977872, 2021). "It is notable that 6 male breast cancer patients appeared in the BRCA1 mRNA-high group, whereas none appeared in the BRCA1 mRNA-low group, although this may be due to the larger sample size of BRCA1 mRNA-high patients." (PMID 34611475, 2021). "HR deficiency has been shown to be associated with immunogenicity in breast cancer, but the association of BRCA1/2 mutation and immunotherapy response in non-BRCA-associated cancer types remains unknown." (PMID 34095878, 2021). "Interestingly, the Pro-PrP isoform continues to possess the GPI anchor peptide signal sequence which is able to provide a binding motif for filamin A, which participates in modulating cancer cell proliferation and migration in colorectal cancer cells and the expression of BRCA1 in breast cancer." (PMID 33671884, 2021).
breast cancer (continued). "In this large, consecutive series of unselected patients with breast cancer, all of the patients and physicians were not aware of the BRCA1/2 variant status when they selected BCT or mastectomy, largely depending on the tumor characteristics per se and the preferences of patients and physicians." (PMID 33890992, 2021). "Rather, it has been suggested that, due to its close chromosomal proximity to the breast cancer tumour suppressor BRCA1, it could be a passenger mutation rather than the driver mutation and simply co-deleted with BRCA1." (PMID 34204202, 2021). "There are also studies conducted on promoter methylation states of 100 genes, including BRCA1, CCND2, BCL2, MDR1, IL10, and TWIST, recorded to understand how alteration between hypermethylation and hypomethylation over time contributes to select breast cancer susceptibility biomarkers." (PMID 34576196, 2021). "Identifying the clinical profile of breast cancer women harboring BRCA1 gene hypermethylation may help oncologists to select the subgroup of patients who may be candidates for BRCA1 methylation assessment, thus, possibly enlarging the cancer population who may benefit from new target-therapy agents." (PMID 33808555, 2021). "Other previous studies of young women with breast cancer found lower frequency of BRCA1/2 genetic testing among young breast cancer patients ranging from 21% to 24% reporting that they completed testing, but these studies were based on self-report and limited to BRCA1/2 genetic testing only." (PMID 31802423, 2021). "For instance, genomic alternations such as specific mutations in breast cancer 1 (BRCA1) and breast cancer 2 (BRCA2) genes are well-established tumor biomarkers used for breast cancer risk assessment, meaning that women bearing these mutations are predisposed to develop breast cancer." (PMID 34439360, 2021). "Thus, since the Amerindians were one of the forming group of the Latin Americans, they have similarities in their genomic profile, including the BRCA1 and BRCA2 genes, a fact that can be extremely relevant in the likely high frequency of variants linked to breast cancer in these populations." (PMID 33499154, 2021). "The risk of breast cancer does not appear to be different between BRCA1 and BRCA2 carriers." (PMID 34356066, 2021). "However, high-risk genes such as BRCA1 and BRCA2 account for less than 15% of breast cancer cases, which suggests that numerous breast cancer-related risk genes have not been discovered, and these gene polymorphisms influence susceptibility to breast cancer." (PMID 33632172, 2021). "Breast cancer gene 1 (BRCA1), retinoic acid receptors-b2 (RAR-b2), and RASSF1A are examples of tumor suppressor genes, whose loss of expression in BC is partially attributed to promoter hypermethylation." (PMID 33970384, 2021). "RRSO (risk reducing salpingo-oophorectomy) may have possibly reduced the risk of breast cancer for BRCA2 pathogenic variant carriers but not for BRCA1 carriers." (PMID 34071148, 2021). "We also investigated the effect of reducing Sox11 levels in two transplantable Brca1-deficient oestrogen receptor-negative mouse mammary tumour cell lines, to assess whether Sox11 regulates similar functions in tumour progenitor cells." (PMID 33969421, 2021). "First, 22 women in the TCGA ovarian cancer category had BRCA1 or BRCA2 germline mutations, while another 27 in the control group had BRCA1 or BRCA2 mutations (these were breast cancer patients, included here as controls because they were non-ovarian cancer women patients)." (PMID 33750420, 2021). "In addition, the positive effects of lifestyle modifications, including physical activity and diets rich in fruits and vegetables, were demonstrated by a clinical trial that revealed decreased TNF-α levels in BRCA1/2+ breast cancer survivors following a yearlong lifestyle modification program." (PMID 34950252, 2021).
breast cancer (continued). "The BRCA1/ZBRK1 complex may play a role in the aspartic acid metabolism, and the ZBRK1/ZNF350 gene mutations have been detected in both familial and sporadic breast cancer patients." (PMID 33407485, 2021). "Indeed, 10-year survival was 48% in PALB2 mutation carriers with breast cancer vs. 74.7% in non-mutation carriers with breast cancer and 72% in BRCA1 mutated patients." (PMID 33718150, 2021). "In addition, a prospective multicenter cohort study reported that RRSO significantly reduced the risk of breast cancer for BRCA2 pathogenic variant carriers but not for BRCA1 carriers." (PMID 34071148, 2021). "All the 17 ovarian and breast cancer cell lines were determined, 2 cell lines (11.76%) were mBRCA carriers (only including SNV and InDel variation, which are defined as likely pathogenic and pathogenic mutation carriers), and BRCA1/2 copy number loss was detected in 8 cell lines (47.06%)." (PMID 34814825, 2021). "For both BRCA1 and BRCA2 heterozygotes, the strength of the association was greater for ER-positive contralateral breast cancers compared with ER-negative contralateral breast cancers (in the case of BRCA1, even if the ER-negative PRS was used), although most of the confidence intervals overlapped." (PMID 34113011, 2021). "RASSF1A expression is also silenced by methylation in breast cancer, yet how it is regulated in at-risk but non-cancerous BRCA1/2 gene mutated tissues, in combination with high MD, is unknown." (PMID 34209669, 2021). "Moreover, combined GSK3 and PARP inhibition has yielded encouraging results in BRCA2 deficient or HR proficient colon cancer cells but not on BRCA1 deficient breast cancer HCC1937 cells." (PMID 33589588, 2021). "Thus, BRCA1 and BRCA2 are the most common germline mutated genes, while PIK3CA is the second most common somatic mutated gene in breast cancer patients; however, subtle frequency differences may be related to the age of onset of the disease." (PMID 34287479, 2021). "Indeed, the estimated 20-year risks of developing contralateral breast cancer in this study were higher compared to a previously published study with a prospective design:1 47% versus 40% for BRCA1 heterozygotes and 40% versus 26% for BRCA2 heterozygotes, respectively." (PMID 34113011, 2021). "A total of 51 African women from Burkina Faso affected by breast cancer have been selected by genetic counseling at the CERBA/LABIOGENE laboratory of the University of Ouagadougou (Burkina Faso) to perform a genetic testing for the screening of BRCA1 and BRCA2 genes." (PMID 34717758, 2021). "A recent study on a large prospective cohort showed that the cumulative breast cancer risk to age 80 years was 72% for BRCA1 and 69% for BRCA2 carriers, and the cumulative risk for contralateral breast cancer 20 years after breast cancer diagnosis was 40% for BRCA1 and 26% for BRCA2 carriers." (PMID 33718150, 2021). "In addition, incidences of RRSO and breast cancer in women lacking BRCA1/2 mutation have been reported." (PMID 32862296, 2021). "Talazoparib (oral 1 mg, once daily [QD]) is approved in the US, EU, and other countries as monotherapy for the treatment of patients with human epidermal growth factor receptor 2 (HER2)-negative advanced breast cancer with a germline BRCA1/2 mutation, and is under investigation in other tumor types." (PMID 34160752, 2021). "However, recent clinical trials have indicated that a larger number of patients with breast cancer may be sensitive to PARP inhibitors because of other DNA-repair gene mutations, DNA-repair deficiency, and somatic BRCA1 and BRCA2 mutations." (PMID 34203351, 2021).
breast cancer (continued). "Indeed, although platinum-based therapies are not the standard of care for breast cancer, they can have utility in carriers of pathogenic mutations in BRCA1 and BRCA2 genes, who are particularly sensitive to platinum-based drugs." (PMID 34072979, 2021). "Additional studies have identified BRCA1/2 pathogenic variants in up to 29% of patients of Ashkenazi Jewish ethnicity presenting with TNBC, 20% of those with TNBC diagnosed at a young age and/or with a family history of breast cancer, and 8–14% of those with TNBC unselected for family history." (PMID 34072659, 2021). "For BRCA1 heterozygotes, the largest association was seen with the ER-negative PRS313, while for BRCA2 heterozygotes, both the PRS313 and ER-positive PRS313 showed similar associations with contralateral breast cancer risk that were somewhat larger than the ER-negative PRS313 association." (PMID 34113011, 2021). "In terms of clinicopathological features, as shown in prior studies, the majority of breast cancer cases associated with germline BRCA1 pathogenic variants were hormone receptor-negative tumors (76%) while those arising in BRCA2-mutated patients were hormone receptor-positive (83%)." (PMID 33579978, 2021). "In addition to the BRCA1 and BRCA2 genes, there are other susceptibility genes reported to date as high penetrance and moderate penetrance genes involving in the development of breast cancer." (PMID 34045478, 2021). "The BCRAT tool is an implementation of the Gail model, which is a statistical model that estimates 5-year breast cancer risk in women without a personal history of breast cancer and without known mutations in high-risk breast cancer genes such as BRCA1 and BRCA2." (PMID 34521662, 2021). "Pooled analysis of 16 studies, including 1325 with BRCA1/2 mutation and 8855 with no mutation regarding the overall survival of patients with breast cancer harboring BRCA1/2 mutations, revealed a correlation between the presence of BRCA1/2 mutation and overall survival." (PMID 32862296, 2021). "Women diagnosed with triple negative breast cancer (TNBC: oestrogen, progesterone and human epidermal growth factor receptor 2 [HER2] negative) comprise 10–15% of all breast cancer diagnoses and are more likely to carry a germline BRCA1 pathogenic variant (PV) than hormone positive breast cancers." (PMID 33637119, 2021). "However, how the various cells residing in the TME of germline BRCA1/BRCA2-deficient breast tumors that are equally impaired by the same germline mutation contribute to the pathogenesis of the hereditary breast cancer has not been consistently addressed." (PMID 33540843, 2021). "High-ranking Catalogue of Somatic Mutations in Cancer (COSMIC) Breast Cancer gene (BRCA) point mutational signature cosegregates with a high prevalence of structural variants, termed the unstable genomic subtype, and deleterious mutations in HR repair pathway genes such as BRCA1 and 2 and PALB24." (PMID 33039466, 2021). "Identifying the clinical profile of breast cancer in women harboring BRCA1 gene hypermethylation may help oncologists select a subgroup of patients who may be candidates for BRCA1 methylation assessment, thus, possibly enlarging the cancer population who may benefit from new target-therapy agents." (PMID 33808555, 2021). "While curing breast cancer during pregnancy would be challenging, the use of PARP inhibitors has garnered much enthusiasm, and several such agents have been approved by the FDA for the treatment of patients with ovarian and breast cancers harboring inherited BRCA1 and/or BRCA2 mutations." (PMID 33854442, 2021).